CXCL1 (C-X-C motif chemokine ligand 1)
Diseases named in the same sentence as CXCL1 in open-access papers (continued):
Sharing a sentence is not in itself a finding about the gene and the disease.
bacterial meningitis (6 papers, 2004 to 2022). Inflammation of the membranes surrounding the brain and spinal cord due to a bacterial infection. "Bacterial meningitis has been reported to induce robust CXCL1 expression in microglia and astrocytes." (PMID 35742984, 2022). "We focused on the neutrophil chemokines IL-8 and CXCL-1 as these cytokines are highly induced during bacterial meningitis and we observed an increase in neutrophilic infiltrate in brain tissue during the development of GBS meningitis in our mouse model." (PMID 31181121, 2019). "Elevated CXCL5, CXCL8, and CXCL1 and TNFα CSF concentrations have been reported in children with bacterial meningitis." (PMID 31727097, 2019). "In bacterial meningitis, the majority (23/36) of examined cytokines displayed elevated values with CCL7, TNF-α, CXCL1, and IFNγ showing consistent results with the literature (; Pinto)." (PMID 31727097, 2019). "Additionally, pyroptosis causes the excessive production of cytokines and chemokines including TNF-α, IL-1β, IL-6, CCL3, CXCL-1, CXCL-2, etc. in bacterial meningitis which can also result in inflammatory mediator-induced neuronal damage." (PMID 26683708, 2015). "The CXCL1 chemokines, macrophage inflammatory protein-2 (MIP-2) and cytokine-induced neutrophil chemoattractant (KC), have been shown to play a role in a number of pathophysiological disease states including endotoxin-induced inflammation and bacterial meningitis." (PMID 15274748, 2004).
bacterial pneumonia (6 papers, 2012 to 2025). Acute infection of the lung parenchyma caused by bacteria (e.g., Streptococcus pneumoniae, Haemophilus influenzae, Chlamydia pneumoniae, Mycoplasma pneumoniae, and Legionella pneumophila). "We identified that the mutant lacking SasD (S. aureus surface protein D; sasD::Tn) induced reduced levels of cytokines G-CSF, CXCL1, MCP-1, and IL-1β compared to the WT strain during bacterial pneumonia." (PMID 36040164, 2022). "Because cytokines are important regulators of the inflammatory response to bacterial pneumonia, we measured pulmonary (TNF-α, IL-6, IL-10, CXCL1) and systemic (TNF-α, MCP-1, IL-6, IFN-γ, IL-10, IL12p70) cytokine and chemokine levels." (PMID 26215706, 2014).
colon adenocarcinoma (6 papers, 2018 to 2023). "In colon adenocarcinoma, CXCL1, CXCL2, and CXCL3 negatively correlated with EMT, while CXCL5, CXCL6, PPBP, and CXCL8 positively correlated with EMT." (PMID 37686093, 2023). "For example, in colon adenocarcinoma, the expression of CXCL1, CXCL2, and CXCL3 negatively correlated with EMT, whereas the expression levels of CXCL5, CXCL6, PPBP, and CXCL8 positively correlated with EMT." (PMID 37686093, 2023). "As a result, the role of CXCL1 in the diagnosis and prognosis of colonic adenocarcinoma was investigated in this study (COAD)." (PMID 35958781, 2022). "In the Notterman colon dataset, the mRNA expression levels of CXCL1 in colon adenocarcinoma were increased (fold change = 12.328, P = 7.62E-9)." (PMID 34233297, 2021). "Our experimental data establish that among NF-κB target genes, Uev1A-regulated CXCL1 expression plays a critical role in colon cell invasion and metastasis, a notion supported by the colon adenocarcinoma survey." (PMID 29662619, 2018).
Crohn disease (6 papers, 2008 to 2026). A gastrointestinal disorder characterized by chronic inflammation involving all layers of the intestinal wall, noncaseating granulomas affecting the intestinal wall and regional lymph nodes, and transmural fibrosis. "Chemokines implicated in Crohns disease are numerous, some includes CCL2, 4, 5, 8 and 20, and CXCL1, 2, 3, 8, 10, which are expressed by several of our cocktail treated DCs." (PMID 20663192, 2010). "We may further highlight CXCL1 because it is involved in the crosstalk of periodontitis and Crohn’s disease." (PMID 37762294, 2023).
IgA nephropathy (6 papers, 2013 to 2024). "For example, urinary and serum levels of CXCL8/IL8 are elevated in diabetic kidney disease, and CXCL1 has been described to be associated with interstitial fibrosis in progressive IgA nephropathy." (PMID 34064989, 2021). "The results revealed that patients with IgA nephropathy had higher urinary levels of CXCL1 and TGF-β1, and the increased urinary levels of CXCL1 and TGF-β1 were also associated with severe clinical and histological manifestations." (PMID 24023680, 2013). "To further evaluate the significance of CXCL1 and TGF-β1 in IgA nephropathy, we detected urinary CXCL1 and TGF-β1 in patients with IgAN." (PMID 24023680, 2013). "TLR3 ligation in human mesangial cells promotes the secretion of the neutrophil chemoattractant CXCL1 and CXCL1 is also expressed in diagnostic biopsies from patients with lupus nephritis but not in biopsies of patients with IgA nephropathy." (PMID 29650017, 2018). "Correlation between the urine TWEAK, CXCL1, CXCL12, MCP1, and TRAIL protein with severity of IgA nephropathy." (PMID 39492831, 2024). "IgG-ddIgA1 complexes from both patients with IgA nephropathy (IgAN-IgG-dd-IgA1) and healthy controls (HC-IgG-dd-IgA1) could induce the proliferation of mesangial cells and up-regulate expression of MCP-1, IL-6 and CXCL1." (PMID 28969604, 2017). "IgG-ddIgA1 complexes from both patients with IgA nephropathy (IgAN-IgG-ddIgA1) and healthy controls (HC-IgG-ddIgA1) could induce the proliferation of mesangial cells and up-regulate the expression of multiple inflammatory cytokines, including IL-6, MCP-1 and CXCL1." (PMID 28969604, 2017).
keratitis (6 papers, 2009 to 2023). A corneal disease that is characterized by inflammation of the cornea. "As per mirror of the biomolecular changes occurring after leucocytes infiltration, specific ELISA kits revealed a marked increase of both the PMN‐produced cytokine CXCL1/KC and the macrophage‐produced IL‐10 24 hours after the induction of keratitis." (PMID 33058526, 2020). "Study in LPS induced keratitis models of mice showed that the expression of CXCL1 increased and it plays an important role in the expression of chemokine and neutrophil infiltration." (PMID 26036769, 2015). "Using a mouse keratitis model, caveolin-1-/- mice showed reduced entry of virus as compared to wild type mice and showed reduced levels of both pSrc and CXCL1 expression complimenting our in vitro data." (PMID 24147000, 2013). "CXCL1 was shown to be temporally up regulated in an LPS treated sterile keratitis model in the mouse, but its increase in lumican-deficient corneas was lower than that of wild types." (PMID 23358433, 2013). "In agreement with these sterile keratitis findings, after infection with P. aeruginosa, we also noted a rapid increase in CXCL1." (PMID 23358433, 2013). "It has been shown by others that in the sterile LPS-keratitis model, CXCL1 is up regulated within 3 hrs of injury, with maximum induction 24 hrs after injury and subsiding by 72 hrs." (PMID 23358433, 2013). "Because neutrophils appeared by histology and flow cytometry to be the predominant infiltrating cell in HAdV-D53 keratitis, we also tested the expression of neutrophil chemokines CXCL1 and CXCL2." (PMID 19492050, 2009). "Similarly, CXCL1 levels in the sterile LPS-keratitis model was reportedly increased in the anterior chamber of mice deficient in lumican and keratocan, another corneal proteoglycan." (PMID 23358433, 2013).
liver cirrhosis (6 papers, 2013 to 2024). "As a consequence of this, patients with the CXCL1 rs4074 A allele have a greater predisposition to liver cirrhosis as a result of chronic HCV infection." (PMID 35806156, 2022). "The level of CXCL1 expression in the liver is associated with disease progression, stages of liver fibrosis and liver cirrhosis." (PMID 35806156, 2022). "The present study addressed the question, whether the CXCL1 rs4074 polymorphism predisposes to liver cirrhosis in patients with chronic alcohol abuse (>300g/week)." (PMID 24260493, 2013). "Specifically, more patients with liver cirrhosis and HCC have the CXCL1 rs4074 A allele, implying that this allele is associated with a predisposition to these diseases." (PMID 37408240, 2023). "This cancer, similar to liver cirrhosis, is characterized by inflammatory responses in which CXCL1 plays a significant role." (PMID 37408240, 2023). "During exposure of the liver to agents leading to liver cirrhosis and HCC, NF-κB is activated and CXCL1 expression increases." (PMID 37408240, 2023). "CXCL1, IL-1β, and TNF-α were obviously increased in the liver cirrhosis group compared with the control group." (PMID 37273916, 2023). "CXCL1 expression is higher in HCC tumors than in healthy liver tissue, and is higher in HCC than in liver cirrhosis." (PMID 37408240, 2023). "In addition, LSECs induce liver cirrhosis and PHTN by recruiting infiltrated neutrophils in a CXCL1-dependent manner and infiltrated proinflammatory macrophages in a CCL2-dependent manner." (PMID 38713515, 2024). "Moreover, we next measured the levels of the inflammatory cytokines, including IL-6, CXCL1, IL-1β, and TNF-α, in the intestine to examine the role of liver cirrhosis on inflammatory response following vitamin D treatment." (PMID 37273916, 2023). "Furthermore severity of liver cirrhosis, indicated by the model of end-stage liver disease (MELD) score, was comparable between patients who carried the A allele of the CXCL1 rs4047 polymorphism and patients without this allele (mean 16.7 versus 16.8; p=0.639)." (PMID 24260493, 2013).
osteoarthritis (6 papers, 2008 to 2022). A noninflammatory degenerative joint disease occurring chiefly in older persons, characterized by degeneration of the articular cartilage, hypertrophy of bone at the margins and changes in the synovial membrane. "CXCL1 promotes the expression of IL6 in synovial fibroblasts of osteoarthritis and RA patients via the CXCR2, c-Raf, MAPK, and AP-1 pathways." (PMID 35707715, 2022). "CXCL1 in the synovial fluid of osteoarthritis patients correlated with the severity of pain." (PMID 34615455, 2021). "SHH autocrine treatment of osteoarthritis MSC stimulates proliferation, chondrogenesis, hypertrophy, and replicative senescence with elevated SASP gene expression including IL1B, IL6, CXCL1, and CXCL8." (PMID 34646822, 2021). "In our study, catabolic genes, including MMP-3 and -9 and ADAMTS5, and the proinflammatory cytokines, including CCL-2 and-5 and CXCL1, were also inhibited by DHA treatment, suggesting the potential role of DHA in maintaining cellular homeostasis and treating osteoarthritis." (PMID 27941926, 2016).
osteoporosis (6 papers, 2022 to 2025). A condition of reduced bone mass, with decreased cortical thickness and a decrease in the number and size of the trabeculae of cancellous bone (but normal chemical composition), resulting in increased fracture incidence. "By promoting osteoblast autophagy and inhibiting ferroptosis, CXCL1 may help maintain bone homeostasis and prevent bone degradation associated with osteoporosis." (PMID 41165410, 2025). "Serum CXCL1 levels are positively associated with human osteoporosis and may cause osteoporosis by accelerating cell senescence, mediating chronic inflammation, and promoting the migration and maturation of osteoclast progenitors." (PMID 38601464, 2024). "In addition, XLGB can prevent estrogen-deficient osteoporosis through ERα upregulation of CXCL1/2, elucidating the anti-osteoporosis mechanism of the systemic regulatory effect of XLGB." (PMID 36769267, 2023). "Future research should explore how CXCL1 modulation affects bone remodelling in animal models of osteoporosis, assessing parameters such as bone density, biomechanical strength and histological changes in bone tissue." (PMID 41165410, 2025). "By elucidating the mechanisms through which CXCL1 regulates ferroptosis and autophagy, this research aims to identify a potential therapeutic strategy for osteoporosis." (PMID 41165410, 2025). "Due to the induction of osteoclast maturation by CXCR2 ligands, CXCL1 levels are positively correlated with osteoporosis in humans." (PMID 35457023, 2022). "Collectively, our results highlight CXCL1 as a promising therapeutic target for osteoporosis." (PMID 41165410, 2025). "Our findings position CXCL1 as a promising target for osteoporosis treatment." (PMID 41165410, 2025). "CXCL1‐targeted therapies could complement existing osteoporosis treatments, particularly for patients with elevated oxidative stress or iron levels, which exacerbate bone loss." (PMID 41165410, 2025). "However, further in vivo studies will be essential to determine whether modulating CXCL1 expression can directly impact bone health and prevent osteoporosis progression in physiological settings." (PMID 41165410, 2025). "Notably, Hu and colleagues observed an inverse correlation between CXCL1 and CCL2 in serum samples from 24 patients, suggesting that these cytokines may serve as potential novel predictors of early bone loss and be clinically relevant for the diagnosis and prevention of osteoporosis." (PMID 40723413, 2025).
pneumococcal pneumonia (6 papers, 2011 to 2023). A febrile disease caused by STREPTOCOCCUS PNEUMONIAE. "In conclusion, we demonstrate that chronic ethanol exposure in mice is associated with increased bacterial load and decreased leukocyte migration during pneumococcal pneumonia, even in the presence of higher levels of CXCL1." (PMID 37275853, 2023). "Alcohol-fed mice showed increased production of nitric oxide and CXCL1 in alveoli and plasma during pneumococcal pneumonia." (PMID 37275853, 2023). "CXCL1 promotes neutrophils trafficking into lung tissue, which predominate the cellular infiltrates during pneumococcal pneumonia." (PMID 26973817, 2016). "Moreover, during mouse pneumococcal pneumonia, combined treatment with flagellin and antibiotics augmented the release of Cxcl1 and Ccl20 in bronchoalveolar lavage fluid, the influx of neutrophils, and host defense, as reflected by a reduced bacterial burden in the lung." (PMID 38203480, 2023). "Additionally, it would be useful to determine which subset of pulmonary cells are expressing Cxcl1, Cxcl2 and Csf3, as this may yield a focused therapeutic target to improve health outcomes in alcohol consumers with pneumococcal pneumonia." (PMID 35603143, 2022). "Type I IFNs can inhibit chemokine (e.g. CXCL1 and CXCL2) expression and thereby reduce recruitment of neutrophils to the site of infection in case of secondary pneumococcal pneumonia." (PMID 21625574, 2011). "Finally, secretion of CXCL1 (KC) and CXCL2 (MIP‐2) precedes neutrophil recruitment in a model of pneumococcal pneumonia in mice." (PMID 29119707, 2018).
schizophrenia (6 papers, 2012 to 2024). A major psychotic disorder characterized by abnormalities in the perception or expression of reality. "We identified seven inflammation markers linked to schizophrenia onset, which all passed the Bonferroni correction for multiple comparisons (bNGF, GROA(CXCL1), IL-8, M-CSF, MCP-3 (CCL7), TNF-β, CRP)." (PMID 38445386, 2024). "Some earlier reports support an association of CXCL1 and CCL7 with psychotic disorders, although in previous reports their serum level or gene expression has been elevated in patients with schizophrenia." (PMID 25970596, 2015). "Noticeably, as suggested in our study, CXCL1, TLR6 and OSM have been documented to be targeted genes of DNA methylated modification in other diseases, such as schizophrenia, type 1 diabetes and Richter syndrome." (PMID 34017996, 2021). "Among the 13 chemokines studied, a 7 week treatment with OLZ resulted in an increase in two homeostatic chemokines, BCL (CXCL13) and MDC (CCL22), and two inflammatory ones, KC (CXCL1) and TARC (CCL17), all of which were shown to take part in schizophrenia and other mental diseases." (PMID 39457671, 2024). "Our study did not confirm differential expression of CXCL1, but of the other 6 genes, S100A9 (under-expressed in schizophrenia) was found in the Yellow module, one of the modules that is negatively associated to schizophrenia in the medicated dataset." (PMID 22761806, 2012).
ZIKV infection (6 papers, 2018 to 2022). "Top selected ZIKV infection-associated genes from RPE cells are shown in a heatmap that includes multiple immune response genes, such as CCL5, CXCL11, CXCL1, IFNB1, IL6 and TNFSF10." (PMID 30046058, 2018). "ZIKV infection increases the levels of a series of cytokines (IL-1α, IL-6, IL-9, IL-10, IL-12p70, and IFN-γ) and chemokines (CCL2, CCL3, CCL4, CCL5, CCL11, and CXCL1) in mouse brain." (PMID 34399779, 2021). "We show that ZIKV infection activates proinflammatory (IL-1β) cytokines as well as chemokines (CCL2, CCL5, GM-CSF, G-CSF, CXCL1, and CXCL12) in the endothelial cells." (PMID 31249527, 2019). "Finally, as demonstrated during 1-MT treatment, intracranial ZIKV infection also led to increased production of inflammatory mediators, such as CCL5 and CXCL1 in both WT and IDO-1-/- ZIKV mice." (PMID 34335614, 2021).
acne (5 papers, 2019 to 2025). An inflammatory process of the sebaceous glands which is characterized by comedones, nodules, papules and/or pustules on the skin. "The Zn-de-Model group exhibited higher levels of these cytokines than the Model group, with increases of 51.74% for TNF-α, 11.91% for IL-1β, 118.06% for IL-17A, 19.64% for MMP9, and 17.05% for CXCL1/KC, indicating that Zn deficiency leads to more severe skin inflammation in acne-like mice." (PMID 40507073, 2025). "All these genes encode proinflammatory cytokines and chemokines previously detected in acne lesions and are linked to activation of the NF-κB pathway, inducing the upregulation of TNF-α, CXCL8/IL-8, IL-1β, CXCL1 and CXCL2." (PMID 35563458, 2022). "CXCL1/keratinocyte-derived chemokine (KC), CXCL2/MIP2 and CXCL5-6/lipopolysaccharide-induced CXC chemokine (LIX) were regarded as functional homologues of IL-8, where CXCL1, CXCL2 and CXCL6 are identified as candidates associated with acne pathogenesis in humans." (PMID 32707723, 2020).
Allergy (5 papers, 2021 to 2025). An allergy is an immune response or reaction to substances that are usually not harmful. "CXCL1 is involved in airway inflammation, and its presence in the airways of asthmatic patients and animal models of allergy has been linked to increased levels of IL-17 and neutrophil activation." (PMID 40943268, 2025). "The chemokines CXCL-1, -6, and -8 that were upregulated in the S + C group, have also been linked to allergy." (PMID 36452260, 2022). "Even in non-Th2 allergies, IL-17 induces airway epithelial cells to produce chemokines CXCL1 and CXCL8 to promote neutrophil recruitment while stimulating fibroblasts and macrophages to secrete cytokines such as GM-CSF, TNF, IL-1, IL-8, and IL-6 to enhance inflammatory responses." (PMID 35855823, 2022). "Intrathecal injection of anti-CXCl1 antibodies has been found to successfully alleviate pain hypersensitivity induced by spinal nerve ligation, and CXCR2 antagonists can definitively terminate CXCl1-induced thermal pain allergy." (PMID 36204142, 2022). "Indeed, during allergy and anti-helminth immunity, epithelial cells of damaged barriers release alarmins including IL-25, IL-33, and thymic stromal lymphopoietin (TSLP), but also chemokines such as CXCL1 and CCL11, to promote cell recruitment and inflammation." (PMID 40943268, 2025).
Autoimmunity (5 papers, 2010 to 2024). The occurrence of an immune reaction against the organism's own cells or tissues. "IL-17 plays a key role in chronic inflammatory disorders and autoimmunity, and this cytokine stimulates chemokines (e.g., CXCL1, CXCL2 and CXCL8) and granulopoiesis." (PMID 35641947, 2022). "In psoriatic lesions, cytokines like IL-6, IL-12p70, IFNγ and TNFα are identified, together with chemokines like CCL2-5 and CXCL1, which shows that several of the cocktails stimulate cytokines and chemokines that to a large extent overlap with the ones expressed in different autoimmune conditions." (PMID 20663192, 2010).